FGFR2 (fibroblast growth factor receptor 2)
Diseases named in the same sentence as FGFR2 in open-access papers (continued):
Sharing a sentence is not in itself a finding about the gene and the disease.
skin cancer (6 papers, 2009 to 2025). "The primary aim of this research was to evaluate the activation of NOTCH1 and FGFR2 oncogenes in inducing skin cancer in FVB/N mice through a stepwise chemical process." (PMID 39063983, 2024). "Future studies incorporating male mice would be essential to comprehensively understand any potential sex-specific differences in the activation of NOTCH1 and FGFR2 oncogenes and their role in skin cancer induction." (PMID 39063983, 2024). "This study aims to evaluate the activation of NOTCH1 and FGFR2 oncogenes in inducing skin cancer in FVB/N mice through a stepwise chemical process, providing new insights into their involvement in cSCC development." (PMID 39063983, 2024). "In skin cancers, the role of FGFR2 is not completely understood." (PMID 40724880, 2025). "Genetic variants of FGFR4 and FGFR2 seem, therefore, to function as potential biomarkers for progression rather than as a risk factor of skin cancer development." (PMID 22007305, 2011). "Given the power of this study, we did not detect any contribution of genetic variants in the FGFR2 or FGFR4 genes to inherited predisposition to skin cancer among Caucasian women." (PMID 19500394, 2009). "In conclusion, we did not detect any contribution of genetic variants in the FGFR2 or FGFR4 genes to inherited predisposition to skin cancer among Caucasian women." (PMID 19500394, 2009). "Neither mutations in FGFR4 nor in FGFR2 as a possible contribution to an inherited predisposition to skin cancer, could, however, be detected in healthy caucasian women." (PMID 22007305, 2011). "Recent studies have highlighted the roles of various oncogenes in skin cancer, including NOTCH1 and FGFR2." (PMID 39063983, 2024).
astrocytoma (5 papers, 2013 to 2024). "IDH‐mutant astrocytoma grade 4 group exhibited a higher frequency of alternations in FGFR2, CDK6, and MYC." (PMID 38970209, 2024). "Alterations of CDK6, CDKN2A, CDKN2B, FGFR2, and MYC were more likely to be detected in WHO grade 4 astrocytoma, while variations of chromosome 19q had a higher frequency in WHO grade 2–3 astrocytoma." (PMID 38970209, 2024). "The chromatin modifiers pathway and RTK/PI3K/AKT pathway were the two most frequent alternative pathways in IDH‐mutant primary astrocytoma, WHO grades 4, and FGFR2 alternations were detected in 6% of them." (PMID 38970209, 2024).
colorectal tumors (5 papers, 2014 to 2022). "In another study, FGFR2 (hub gene in Subnetwork 7) is reported to promote the PD-L1 expression via the JAK/STAT3 signaling in colorectal tumors and associated with disease progression and poor survival." (PMID 34790220, 2021). "Thus, better characterizing colorectal tumors for FGFR2 amplification could identify a subset of patients who may benefit from FGFR TKI therapies." (PMID 28835367, 2017). "Finally, our in vitro and in vivo results suggest that FGFR small molecule inhibitors in clinical development might provide benefit in colorectal tumors harboring FGFR2 overexpression or amplification." (PMID 24968263, 2014). "To validate this tumor-specific fibroblast infiltration, we analyzed the expression of stromal cell subtype markers CD24, CD26, NT5E, FAP, and FGFR2 in colorectal tumor and non-malignant large intestine samples by flow cytometry." (PMID 35365629, 2022).
COVID-19 (5 papers, 2021 to 2024). A disease caused by infection with severe acute respiratory syndrome coronavirus 2. "Similarly, we suggested several drugs, such as FGFR2 inhibitors which have been used for the treatment of neoplasm can be considered to lower the risk of COVID-19." (PMID 38575325, 2024). "CYLD is upregulated in both COVID-19 and cardiomyopathy and was found to correlate with the activation of FGFR2, an important promoter of inflammation, and TXA2, a gene that is upregulated in platelets (Figure A2A)." (PMID 34071557, 2021). "Notably, in the proteins related to COVID-19, we also found several proteins involved in apoptosis, such as FGFR2 and ERBB4." (PMID 38575325, 2024). "Drug targeting FGFR2 has been hypothesized to be used as treatments for COVID-19 but this has not been tested in trials." (PMID 38575325, 2024).
developmental delay (5 papers, 2021 to 2024). "Therefore, WDR11 and FGFR2 deletions might be responsible for the clinical characteristics of the present case, such as global developmental delays, cardiac defects and facial abnormalities." (PMID 34256807, 2021). "The WES approach allowed us to identify five clinically relevant variants in the GZF1, NFIX, TRRAP, FGFR2 and PAX2 genes associated with Larsen, Malan, developmental delay with or without dysmorphic facies and autism, LADD1 and papillorenal syndromes." (PMID 38909058, 2024).
endometriosis (5 papers, 2019 to 2025). The growth of functional endometrial tissue in anatomic sites outside the uterine body. "Specifically, the upregulation of FGFR2 expression holds the capacity to trigger excessive FGFR2 signal transduction, potentially playing a role in the pathogenesis of endometriosis." (PMID 38384812, 2024). "The growth, migration, invasion, and transforming growth factor-β1 (TGF-β1)-triggered EMT of ESCs were examined to evaluate the role of FGFR2 in endometriosis." (PMID 35311468, 2022). "In contrast with the normal tissues, both eutopic and ectopic endometria from patients with endometriosis had remarkably higher FGFR2 levels." (PMID 35311468, 2022). "The high expression levels of FGFR2 in endometriosis tissues were also confirmed using qRT-PCR (p < 0.05) and western blot analysis." (PMID 35311468, 2022). "By searching the GSE171154, GSE86543, and GSE77182 datasets, FGFR2 was identified as an upregulated overlapping gene in endometriosis." (PMID 35311468, 2022). "FGFR2 was demonstrated to be highly expressed in the ectopic endometrium of women with endometriosis." (PMID 35311468, 2022). "Further studies confirmed that FGFR2 was highly expressed in the ectopic endometrium of patients with endometriosis than in eutopic and normal endometria." (PMID 35311468, 2022). "Considering that FGFR2 is highly expressed in endometriosis, the fundamental involvement of FGFR2 in disease development was studied." (PMID 35311468, 2022). "The ERK signaling pathway, in contrast to p38 and JNK signaling pathway, was shown to be a downstream signaling pathway for FGFR2 in the disease progression of endometriosis." (PMID 35311468, 2022). "Further studies demonstrated that ERK signaling, rather than p38 and JNK signaling, is a downstream signaling pathway responsible for FGFR2 effects in endometriosis." (PMID 35311468, 2022). "Although endometriosis is considered to have cancer-like features, such as uncontrolled cell proliferation, local invasion, and apoptosis resistance, less attention has been paid to the expression of FGFR2 in endometriosis." (PMID 35311468, 2022). "By performing in vitro studies on primary ESCs collected from women with endometriosis, FGFR2 was found to be effective in promoting ESC proliferation, migration, and invasion and inhibiting apoptosis." (PMID 35311468, 2022). "ERK signaling, in contrast to p38 and JNK signaling, was found to be a downstream signaling pathway contributing to FGFR2 and exerting its effects in endometriosis." (PMID 35311468, 2022). "By analyzing the GSE171154, GSE86543, and GSE77182 datasets, FGFR2 was identified as an upregulated gene in endometriosis." (PMID 35311468, 2022). "This is in contrast with our finding that FGFR2 was downregulated in the mid-secretory phase eutopic endometrium of women with endometriosis—a telomerase abundant tissue." (PMID 33317189, 2020). "Potential oncogenic mutations found included PIK3CA, KRAS, PIK3R1, and FGFR2 in benign epithelial endometrium from women with uterine fibroids, and ARID1A mutations in endometrial stroma from women with endometriosis." (PMID 31717878, 2019). "FGFR2 promotes the proliferation, migration, and invasion of ESCs via activation of the ERK signaling pathway in endometriosis: an ERK1/2 inhibitor could counteract the effects of FGFR2 on ESC proliferation and invasion." (PMID 40130159, 2025). "These conclusions suggest that FGFR2 could be a potential therapeutic target for the treatment of endometriosis." (PMID 35311468, 2022). "However, there are no studies available that have reported the expression and effects of FGFR2 in endometriosis." (PMID 35311468, 2022). "The expression and functional effects of FGFR2 in endometriosis were also studied." (PMID 35311468, 2022). "This study aimed to determine the role of FGFR2 in endometriosis." (PMID 35311468, 2022).
endometriosis (continued). "Furthermore, the ERK1/2 inhibitor PD98059 was used to treat ESCs to reveal the involvement of ERK signaling in FGFR2-mediated endometriosis." (PMID 35311468, 2022). "The effects of FGFR2 on endometriosis might be mediated via the activation of ERK signaling." (PMID 35311468, 2022). "In the present study, differentially upregulated genes in endometriosis were analyzed from the GSE171154, GSE86543, and GSE77182 datasets, and FGFR2 was identified as an overlapping gene." (PMID 35311468, 2022). "In the current study, FGFR2 was screened from three datasets (GSE171154, GSE86543, and GSE77182) as an upregulated overlapping gene in endometriosis." (PMID 35311468, 2022). "FGFR2 and PIK3C2A have both previously been proposed to contribute to endometriosis-related carcinogenesis, but their role in benign endometriosis has not been elucidated." (PMID 33317189, 2020).
gallbladder cancer (5 papers, 2021 to 2025). "While FGFR2 fusions are commonly found in ICC, KRAS mutations are frequent in ECC and gallbladder cancer and significantly associated with poor prognosis." (PMID 33921232, 2021).
head and neck squamous cell carcinoma (5 papers, 2016 to 2022). A squamous cell carcinoma that arises from any of the following anatomic sites: lip and oral cavity, nasal cavity, paranasal sinuses, pharynx, larynx, and salivary glands. "In addition to recurrent integrations in RAD51B, NR4A2, and TP63, additional genomic alterations were found in receptor tyrosine kinases, primarily FGFR2 and FGFR3, in HPV-positive head and neck squamous cell carcinoma." (PMID 27154171, 2016). "Moreover, Marshallet al. showed that FGFR2 and FGFR3 are commonly expressed in head and neck squamous cell carcinoma (HNSCC) cells and are activated by autocrine FGF2." (PMID 36111743, 2022).
Hypertension (5 papers, 2015 to 2025). The presence of chronic increased pressure in the systemic arterial system. "Variants FGFR2 rs199545667 and rs4752570, along with FGFR4 rs351855, showed significant associations with elevated blood pressure and hypertension prevalence." (PMID 41573461, 2025).
lymphoma (5 papers, 2018 to 2024). A malignant (clonal) proliferation of B- lymphocytes or T- lymphocytes which involves the lymph nodes, bone marrow and/or extranodal sites. "Since FGFR2 pathway interacts with major signalling pathways, including BMP, WNT, Notch and Hedgehog, its aberrant activity is associated with developmental defects resulting in metabolic disorders, and cancer including lymphoma." (PMID 30857150, 2019).
multiple myeloma (5 papers, 2014 to 2024). "Moreover, translocation at the FGFR2 locus have been previously reported in multiple myeloma and myeloproliferative disorders." (PMID 37509244, 2023). "Endothelial cells (ECs) isolated from the bone marrow of multiple myeloma patients (MMECs) express EC markers, including Tie2, vascular endothelial growth factor receptor-2 (VEGFR-2), fibroblast growth factor receptor-2 (FGFR-2), CD105-endoglin and vascular endothelial (VE)-cadherin." (PMID 26919105, 2016).
oral squamous cell carcinoma (5 papers, 2015 to 2019). "FGFR2 mutations also occur in oral squamous cell carcinoma, and a patient with OSCC was found to respond to pazopanib, a multiple tyrosine kinase inhibitor." (PMID 28384236, 2017). "For example, in oral squamous cell carcinoma, miR-381-3p suppressed cell proliferation and cell cycle progression while enhanced apoptosis through directly targeting fibroblast growth factor receptor 2 (FGFR2)." (PMID 30309377, 2018). "We observed expression of FGF-2 and its receptors FGFR-2 and FGFR-3 in neoplastic progression from normal through stages of epithelial dysplasia to oral squamous cell carcinoma." (PMID 26465941, 2015).
pancreatic adenocarcinoma (5 papers, 2008 to 2025). "AS events of FGFR-2, SPAR, COL6A3 in pancreatic adenocarcinoma have also been previously reported 30-32, and an increase in AS of the KLF6 cancer suppressor gene is associated with pancreatic adenocarcinoma prognosis and tumour grade 33." (PMID 33976726, 2021).
papillary thyroid carcinoma (5 papers, 2013 to 2022). "Therefore, we decided to examine the expression of both FGFR-2 isoform, FGFR-2-IIIb and FGFR-2-IIIc, in different histological thyroid variants such as hyperplasia, follicular adenoma and papillary carcinoma." (PMID 23977259, 2013). "To this aim, we investigated the expression of both FGFR-2 isoforms in thyroid hyperplastic tissues, thyroid follicular adenoma and papillary carcinoma by immunohistochemical procedures and Real-Time PCR analyses." (PMID 23977259, 2013). "We confirmed through Real-Time PCR analysis a relevant down-modulation of both FGFR-2 isoforms in follicular adenoma and papillary carcinoma, with respect to normal thyroid tissue." (PMID 23977259, 2013). "Furthermore, it was also proved that miR-1266-3p inhibited the metastasis in papillary thyroid cancer cells by targeting FGFR2." (PMID 35433237, 2022). "Interestingly, in both follicular adenoma and papillary carcinoma samples we observed a strongly reduced expression of both FGFR-2 isoforms." (PMID 23977259, 2013). "Also in papillary carcinoma, we could observe no FGFR-2-IIIb staining in cytoplasm or membrane (D’, arrows in panel D’)." (PMID 23977259, 2013).
pituitary adenomas (5 papers, 2013 to 2020). "FGFR2, and specifically, the predominat isoform FGFR2-IIIb) is downregulated in half of the pituitary adenomas, possibly due to increased promoter methylation, with potential implication for the expression of certain cyclin dependent kinases (such as p21 and p27)." (PMID 31877737, 2019). "Although DNA methylation-induced PDGFRα and FGFR2 silencing has been reported in CG4 cells or primary human pituitary adenomas, the role of DNA methylation in regulating the expression level of these co-different genes and their effects on myogenesis or adipogenesis still remains unclear." (PMID 33308295, 2020). "In contrast, FGFR-2 has been shown to be downregulated in pituitary adenomas due to FGFR-2 promoter methylation; however, this has not been clinically assessed in relation to tumor invasiveness or aggressiveness." (PMID 32012988, 2020).
pituitary tumor (5 papers, 2013 to 2025). A benign or malignant neoplasm affecting the pituitary gland. "Promoter methylation epigenetically silences the FGFR2 (Fibroblast Growth Factor Receptor 2) gene in pituitary tumors." (PMID 40362297, 2025). "Epigenetic modifications affected the FGFR2-IIIb isoform mRNA transcript, in which has relatively lesser abundance in pituitary tumors." (PMID 37445833, 2023). "Tumors with loss of FGFR2 expression and presence of a truncated isoform of FGFR4, the pituitary tumor-derived FGFR4 (pdt-FGFR4), confer invasive growth of pituitary tumor cells and contributes to downregulation of N-cadherin expression." (PMID 31817110, 2019).
rectal cancer (5 papers, 2016 to 2023). A primary or metastatic malignant neoplasm that affects the rectum. "In rectal cancer patients receiving neoadjuvant CRT, it was shown that high expression of FGFR2 was associated with an advanced tumor stage, a poor treatment response, and lower survival." (PMID 37895091, 2023). "In addition, there was positive correlation between advanced tumor stage and a high expression of FGFR2 in rectal cancers." (PMID 27154171, 2016). "Further, factors such as fibroblast growth factor receptor 2 overexpression, ALDH1, and upregulated polo-like kinase in rectal cancer were reported to be predictors of recurrence after NACRT." (PMID 27129578, 2016).
rhabdomyosarcoma (5 papers, 2013 to 2025). A rare aggressive malignant mesenchymal neoplasm arising from skeletal muscle. "The PAX3‐FOXO1 fusion protein in high‐risk rhabdomyosarcomas increases FGFR4, FGFR2, and FGF7 levels." (PMID 34850536, 2022). "Recently, FGFR::TACC fusions have been reported in a variety of non-epithelial cancers, including FGFR1::TACC1 fusions as a novel alternative genetic driver in rhabdomyosarcoma, and FGFR2::TACC2 fusions as a mechanism of multidrug resistance in TKI-treated gastrointestinal stromal tumors (GIST)." (PMID 39387893, 2025). "Additionally, high expression levels of FGFR2 and FGF7 have been associated with increased sensitivity to FGFR inhibitors in fusion-gene-positive rhabdomyosarcoma cell lines." (PMID 38491511, 2024). "Furthermore, patient samples exhibit higher mRNA levels of FGFR2 and FGF7 in fusion‐gene‐positive versus fusion‐gene‐negative rhabdomyosarcomas." (PMID 34850536, 2022).
acute myeloid leukemia (4 papers, 2017 to 2023). Acute myeloid leukemia (AML) is a group of neoplasms arising from precursor cells committed to the myeloid cell-line differentiation. "Although predicted in silico to be benign, FGFR2 K41E, identified in an acute myeloid leukemia, was selected for additional study because of its location in the extracellular Ig1 of FGFR2 and its unknown effect on ligand binding in nearby Ig2 and Ig3." (PMID 30761385, 2017). "In contrast, acute myeloid leukemia (LAML) (2.0%), THCA (1.8%), and UVM (1.25%) exhibited very low frequencies of FGFR2 CNVs." (PMID 33968743, 2021).
autism (4 papers, 2015 to 2024). Persistent deficits in social interaction and communication and interaction as well as a markedly restricted repertoire of activity and interest as well as repetitive patterns of behavior. "Independent genetic studies have linked both Negr1 and FGFR2 to autism." (PMID 26793057, 2015). "All these data not only corroborate the already proposed pathogenicity of FGFR2 in neurodevelopmental disorders, including autism and ADHD but also specifically support its etiological role in our patient’s case." (PMID 37733178, 2023).
Breast Invasive Carcinoma (4 papers, 2012 to 2023). "Other cancer types that also had FGFR2 fusion but had much lower fusion rates included LUSC (0.41%), breast invasive carcinoma (BRCA) (0.28%), ovarian serous cystadenocarcinoma (OV) (0.17%), liver hepatocellular carcinoma (LIHC) (0.54%), and THCA (0.4%)." (PMID 33968743, 2021).